AP3B2 (adaptor related protein complex 3 subunit beta 2)
Description:
Subunit of non-clathrin- and clathrin-associated adaptor protein complex 3 (AP-3) that plays a role in protein sorting in the late-Golgi/trans-Golgi network (TGN) and/or endosomes. The AP complexes mediate both the recruitment of clathrin to membranes and the recognition of sorting signals within the cytosolic tails of transmembrane cargo molecules. AP-3 appears to be involved in the sorting of a subset of transmembrane proteins targeted to lysosomes and lysosome-related organelles. In concert with the BLOC-1 complex, AP-3 is required to target cargos into vesicles assembled at cell bodies for delivery into neurites and nerve terminals.
Synonyms: NAPTB; DEE48; EIEE48
Tractability: Antibody: UniProt places it where antibodies can reach, with medium confidence. PROTAC: ubiquitination databases record sites on it; its protein half-life has been measured.
Gene: Protein-coding gene on chromosome 15 (82,659,281 to 82,710,112, reverse strand). Ensembl gene ENSG00000103723.
Subcellular location: Cytoplasmic vesicle, clathrin-coated vesicle membrane; Golgi apparatus
Subcellular location (Human Protein Atlas): Golgi apparatus; Cytosol; Nucleoplasm
Gene Ontology:
Molecular function: AP-3 adaptor complex binding
Biological process: anterograde axonal transport; anterograde synaptic vesicle transport; clathrin-coated vesicle cargo loading, AP-3-mediated; endocytosis; synaptic vesicle coating; synaptic vesicle recycling; intracellular protein transport; synaptic vesicle endocytosis; vesicle-mediated transport
Cellular component: AP-3 adaptor complex; early endosome; intracellular vesicle; axon cytoplasm; clathrin-coated vesicle membrane; Golgi apparatus; membrane coat; neuron projection; presynapse
Genetic constraint (gnomAD): Loss-of-function variants: 50 observed, 121.74 expected, observed/expected ratio (o/e) 0.41, 90% interval 0.33 to 0.52. The upper end of that interval is the gene's LOEUF score, 0.52, which puts it in group 2 of 6, group 1 being the genes least tolerant of losing a copy. Missense variants: 1,177 observed, 1,415.7 expected, observed/expected ratio (o/e) 0.83, 90% interval 0.79 to 0.87. Synonymous variants: 541 observed, 561.47 expected, observed/expected ratio (o/e) 0.96, 90% interval 0.9 to 1.03.
Gene-disease validity (ClinGen):
ClinGen rates the evidence that AP3B2 causes each of these diseases.
genetic developmental and epileptic encephalopathy (autosomal recessive): Definitive. A complex neurodevelopmental disorder characterized by a range of developmental delays and epileptic encephalopathy phenotypes.
Homologues: Orthologues: chimpanzee AP3B2 (99% identical), guinea pig AP3B2 (93% identical), mouse Ap3b2 (93% identical), pig AP3B2 (92% identical), dog AP3B2 (92% identical), rat Ap3b2 (91% identical), rabbit AP3B2 (90% identical), macaque AP3B2 (88% identical), tropical clawed frog ap3b2 (77% identical), zebrafish AP3B2 (67% identical), Drosophila melanogaster rb (53% identical), Caenorhabditis elegans apb-3 (36% identical). Paralogues in human: AP3B1 (62% identical), AP2B1 (23% identical), AP1B1 (22% identical), AP4B1 (16% identical).
Diseases named in the same sentence as AP3B2 in open-access papers:
AP3B2 is named in the same sentence as 42 diseases in open-access papers, as found by Europe PMC text mining. Sharing a sentence is not in itself a finding about the gene and the disease. The quoted sentences say what the papers report.
and epileptic encephalopathy (3 papers, 2025). "AP3B2 gene defect is a rare autosomal recessive variant with developmental and epileptic encephalopathy." (PMID 40230662, 2025). "Furthermore, novel mutations in AP3B2 have been identified in individuals with developmental and epileptic encephalopathies as well as in psychosis." (PMID 40779003, 2025). "However, biallelic variants in AP3B2 are associated with early‐onset epileptic encephalopathy, probably reflecting the neuron‐specific expression of AP3B2, in contrast to AP3B1 and AP3D1 that are expressed in a variety of tissues." (PMID 39420677, 2025).
cerebellar ataxia (3 papers, 2021 to 2025). A neurological syndrome characterized by clumsy and uncoordinated movement of the limbs, trunk, and cranial muscles. "While prior AP3B2-associated cases primarily featured cerebellar ataxia or sensory ataxia, this case uniquely manifests the SCD-like triad (posterior column, pyramidal tract, and peripheral nerve damage)." (PMID 41019034, 2025). "Malignancy was less common in patients with anti-AP3B2 antibody-associated cerebellar ataxia with only 1 in 9 patients identified as having an underlying cancer." (PMID 34489848, 2021). "Anti-neurochondrin antibodies have been described in patients with long-standing cerebellar or brainstem symptoms, while Adapter-related protein complex 3 beta-2 subunit (AP3B2) antibodies are more frequently associated with a subacute form of cerebellar ataxia." (PMID 40881707, 2025). "Neurological disorders associated with anti-AP3B2 antibodies may manifest as cerebellar ataxia, myeloneuropathy, sensory ataxia, dysautonomia, and overlapping manifestations of these conditions." (PMID 41019034, 2025). "The aim of this review article is to focus on recently discovered autoantibodies against neuronal targets identified in syndromes cerebellar ataxia and includes two clinical case examples of adaptor protein-3B2 (AP3B2) and tripartite motif-containing (TRIM)-46." (PMID 34489848, 2021).
Intellectual disability (3 papers, 2021 to 2025). "AP3B2 variants have been associated with early-onset encephalopathy exhibiting seizures, developmental regression and intellectual disability with onset of encephalopathy before one year of age and are localized structurally to defective synaptic vesicles." (PMID 40779003, 2025). "Mutations in the AP3B2 gene have been linked to various neurological disorders, such as seizures, intellectual disability, and neurodevelopmental abnormalities." (PMID 38245687, 2024).
autism (2 papers, 2024 to 2025). Persistent deficits in social interaction and communication and interaction as well as a markedly restricted repertoire of activity and interest as well as repetitive patterns of behavior. "This was followed by the sequential expression of METAP1, a risk gene for autism and schizophrenia, along with AP3B2, a risk gene for developmental delay." (PMID 39363111, 2024). "Our current report is the first report on involvement of AP3B2 gene in etiology of autism." (PMID 40779003, 2025).
chronic periodontitis (2 papers, 2015 to 2022). A chronic inflammatory process that affects the tissues that surround and support the teeth. "Our findings provide direct evidence for the association of FBXO38 and AP3B2 with severe chronic periodontitis in the Han Chinese population." (PMID 26643602, 2015). "In this study, we conducted a two-stage comprehensive evaluation of the genetic susceptibility of FBXO38, AP3B2 and WHAMM with the diagnosis of severe chronic periodontitis." (PMID 26643602, 2015). "Genome-wide association studies showed the relationship of NIN, ABHD12B, WHAMM, AP3B2, and SIGLEC5 with chronic periodontitis." (PMID 36360171, 2022). "Since the underlying molecular mechanisms of periodontitis are still unclear, the effects of the NIN, ABHD12B, WHAMM, AP3B2, and SIGLEC5 genes on periodontitis have not been elucidated." (PMID 36360171, 2022).
Cognitive impairment (2 papers, 2021 to 2025). Abnormal cognition is characterized by deficits in thinking, reasoning, or remembering. "In addition to the AP3B2 gene abnormalities, the AP3B2 autoantibody causes cerebral ataxia and cognitive impairment." (PMID 40230662, 2025).
epilepsy (2 papers, 2024 to 2025). A brain disorder characterized by episodes of abnormally increased neuronal discharge resulting in transient episodes of sensory or motor neurological dysfunction, or psychic dysfunction. "This study highlights the value of WES in identifying genetic variants associated with epilepsy, particularly the novel AP3B2 and PIGB variants." (PMID 40230662, 2025). "This study underscores the value of WES in uncovering genetic variants associated with epilepsy, focusing on two novel findings: AP3B2 (NM_001278512.2: c.3190G > A; p.Val1064Ile) and PIGB (NM_004855.5: c.1664G > C; p.Ter555Serext∗54)." (PMID 40230662, 2025).
microcephaly (2 papers, 2021 to 2025). A congenital or acquired developmental disorder in which the circumference of the head is smaller than normal for the person's age and sex. "The clinical manifestations in patients who inherit autosomal recessive AP3B2 gene variants are EER, postnatal microcephaly, eye atrophy, and growth delay." (PMID 40230662, 2025). "AP3B2 (adaptor-related protein complex 3, beta-2 subunit): EOEE characterized by severe/profound DD, with possible psychomotor deterioration, poor visual contact with optic atrophy, and postnatal microcephaly." (PMID 33919646, 2021).
psychosis (2 papers, 2021 to 2025). "AP3B2 protein is part of the cellular endocytotic machinery, which has previously been implicated in the pathophysiology of psychotic disorders." (PMID 34518517, 2021).
breast carcinoma (1 paper, 2023). "Despite the p-values for AUCs of some genes such as AP3B2, BLOC1S1, NUDT13, PTCH1, and ZNF609 being statistically significant in all three breast cancer subtypes, their significance in HER2+ cancers and TNBC were much lower compared to that in ER+/HER2- breast cancer patients." (PMID 37700842, 2023).
Delusion (1 paper, 2021). A delusion is a fixed false belief held despite evidence to the contrary. "Furthermore, six autoantibodies were associated with specific psychopathology symptoms: anti-AP3B2 (persecutory delusions), anti-TDO2 (hallucinations), anti-CRYGN (initial insomnia); anti-APMAP (poor appetite), anti-OLFM1 (above-median cognitive function), and anti-WHAMMP3 (anhedonia and dysphoria)." (PMID 34518517, 2021).
injury (1 paper, 2025). Damage inflicted on the body as the direct or indirect result of an external force, with or without disruption of structural continuity. "Also, AP3B2 autoantibody may be produced following traumatic brain injury." (PMID 40230662, 2025).
neuroectodermal tumor (1 paper, 2025). "Although AP3B2 antibodies react with neuroectodermal tumor cell lines, they have not been classified as autoimmune disorders associated with paraneoplastic syndromes to date." (PMID 41019034, 2025).
Sensory neuropathy (1 paper, 2025). Peripheral neuropathy affecting the sensory nerves. "In our case, the triad of sensory neuropathy, pyramidal tract involvement, and posterior column impairment is attributable to AP3B2 expression in the dorsal root ganglia, spinal cord, and cerebral cortex." (PMID 41019034, 2025).
Subacute Combined Degeneration (1 paper, 2025). A neuropathy due to VITAMIN B 12 DEFICIENCY or to excessive NITROUS OXIDE inhalation. "We here report the first case of subacute combined degeneration (SCD)-mimic accompanying adaptor protein-3B2 (AP3B2) antibody, expanding the clinical spectrum of AP3B2 antibody-associated disorders." (PMID 41019034, 2025).
neurological disorders (2 papers, 2024 to 2025). "We propose the term anti-AP3B2 antibody-associated SCD-mimic to characterize this novel phenotype, thereby broadening the differential diagnostic spectrum of neurological disorders." (PMID 41019034, 2025). "Thus, AP3B2 itself is unlikely to be a pathogenic autoantigen; rather, AP3B2 autoantibodies may serve as biomarkers for associated neurological disorders." (PMID 41019034, 2025).
AP3B2 also shares sentences with these, for which no sentence is quoted: cancer (3 papers); Angelman syndrome (1); arteritis (1); cerebellar degeneration (1); developmental delay (1); dysautonomia (1); dysphoria (1); Encephalopathy (1); Hallucinations (1); heart disease (1); Hypotonia (1); infantile epileptic encephalopathy (1); insomnia (1); ischemia (1); legionellosis (1); leishmaniasis (1); Macrocephaly (1); melanoma (1); myocardial infarction (1); Neonatal sepsis (1); neurodevelopmental disorder (1); Onset (1); optic atrophy (1); schizophrenia (1); Seizure (1); sensory ataxia (1).